FMNL2 (formin like 2)
Description:
Plays a role in actin cytoskeleton dynamics and regulation of cell shape.
Synonyms: FHOD2; KIAA1902
Tractability: Small molecule: a structure with a bound ligand is known. Antibody: the Human Protein Atlas places it where antibodies can reach. PROTAC: ubiquitination databases record sites on it; its protein half-life has been measured.
Gene: Protein-coding gene on chromosome 2 (152,335,136 to 152,649,831, forward strand). Ensembl gene ENSG00000157827.
Subcellular location: Cytoplasm, cytosol
Subcellular location (Human Protein Atlas): Cytosol; Golgi apparatus; Plasma membrane
Pathways (Reactome):
Signal Transduction: CDC42 GTPase cycle; RHO GTPases Activate Formins; RHOC GTPase cycle
Gene Ontology:
Molecular function: cadherin binding; actin filament binding; actin binding; small GTPase binding
Biological process: cell migration; cortical actin cytoskeleton organization; regulation of cell shape; actin cytoskeleton organization; cytoskeleton organization; regulation of cell morphogenesis
Cellular component: cytosol
Genetic constraint (gnomAD): Loss-of-function variants: 44 observed, 104.3 expected, observed/expected ratio (o/e) 0.42, 90% interval 0.33 to 0.54. The upper end of that interval is the gene's LOEUF score, 0.54, which puts it in group 2 of 6, group 1 being the genes least tolerant of losing a copy. Missense variants: 897 observed, 1,196.7 expected, observed/expected ratio (o/e) 0.75, 90% interval 0.71 to 0.79. Synonymous variants: 411 observed, 424.74 expected, observed/expected ratio (o/e) 0.97, 90% interval 0.89 to 1.05.
Homologues: Orthologues: chimpanzee FMNL2 (100% identical), macaque FMNL2 (99% identical), pig FMNL2 (98% identical), dog FMNL2 (98% identical), rat Fmnl2 (97% identical), guinea pig FMNL2 (97% identical), mouse Fmnl2 (96% identical), tropical clawed frog fmnl2 (88% identical), zebrafish fmnl2a (80% identical), Caenorhabditis elegans daam-1 (19% identical), Caenorhabditis elegans exc-6 (11% identical), Caenorhabditis elegans sydn-1 (5% identical). Paralogues in human: FMNL3 (66% identical), FMNL1 (58% identical), DAAM1 (24% identical), DAAM2 (24% identical), DIAPH3 (22% identical), DIAPH1 (22% identical), DIAPH2 (21% identical), FHOD3 (19% identical), INF2 (19% identical), FMN2 (17% identical), FHOD1 (17% identical), GRID2IP (15% identical), and 6 more.
Diseases named in the same sentence as FMNL2 in open-access papers:
FMNL2 is named in the same sentence as 53 diseases in open-access papers, as found by Europe PMC text mining. Sharing a sentence is not in itself a finding about the gene and the disease. The quoted sentences say what the papers report.
colorectal cancer (18 papers, 2010 to 2024). A primary or metastatic malignant neoplasm that affects the colon or rectum. "Overexpression of FMNL2 in metastatic cell lines and tissues of colorectal carcinoma is associated with more aggressive tumor behavior." (PMID 29258163, 2017). "So far, the role of formins in cancer-associated EMT has remained elusive, apart from a single report demonstrating an association between FMNL2 and colorectal cancer EMT." (PMID 24086398, 2013). "FMNL2 is also involved in the maintenance of epithelial–mesenchymal transition in human colorectal carcinoma cell." (PMID 38747713, 2024). "A growing body of evidence suggests that there is a discrepancy in FMNL2 expression in multiple cancers, for instance, upregulated in colorectal cancer, melanoma, and gastric cancer, but downregulated in hepatocellular carcinoma." (PMID 35379791, 2022). "Previous studies have reported that FMNL2 overexpression is related to invasion and lymphatic metastasis in colorectal cancer." (PMID 35379791, 2022). "CircHIPK3 modulates miR-1207-5p/FMNL2 signal that promotes colorectal cancer cells proliferation and metastasis." (PMID 35443871, 2022). "FMNL2 was also demonstrated to promote cancer malignant development, such as FMNL2 was considered a positive regulator of cell motility and metastasis in colorectal carcinoma." (PMID 35646112, 2022). "Examples of this function are DIAPH1-3 and DAAM1 in breast cancer, DIAPH1 in glioma, FMNL1 in nasopharyngeal carcinoma, FMNL2 in colorectal cancer, and FHOD1 in oral squamous carcinoma." (PMID 34685534, 2021). "Particularly, FMNL2 is disorderly expressed in multiple types of cancers, for instance, gastric cancer, colorectal cancer, melanoma, oral squamous cell carcinoma, and hepatocellular carcinoma." (PMID 34193109, 2021). "The study has pointed out that FMNL2 is significantly upregulated in colorectal cancer, and FMNL2 silence induced by miR-206 upregulation can visibly inhibit the proliferation and invasion of the tumor cells." (PMID 34257650, 2021). "For example, circ_005169 exerted oncogenic function via sponging miR-145 and increasing the expression of E2F5, BAG4, and FMNL2 in colorectal cancer cells." (PMID 28219405, 2017). "In particular, increased FMNL2 expression correlates with increased invasiveness of colorectal cancer (CRC) in vivo and for a variety of CRC cell-lines in vitro." (PMID 27578625, 2016). "These primers were used to amplify individual sections of the entire FMNL2 coding sequence using cDNA prepared from SW480 to SW620 colorectal cancer, and A375 melanoma, cell-lines." (PMID 27578625, 2016). "Increased FMNL2 expression is reported to directly correlate with increased invasiveness in colorectal cancer cell-lines." (PMID 27578625, 2016). "Our findings are distinct from the results reported in a study linking increased FMNL2 expression to metastatic activity in colorectal cancer." (PMID 20633255, 2010). "In colorectal cancer, this miRNA suppresses cell proliferation, migration and invasion through targeting FMNL2, a downstream molecule of a circular RNA related as an oncogene in this type of cancer; its downregulation has also been associated with shorter overall survival rate in patients." (PMID 38146340, 2023). "Moreover, circHIPK3 promotes proliferation and metastasis of colorectal cancer cells via upregulation of FMNL2 by sponging miR-1207-5p." (PMID 35646112, 2022). "Additionally, FMNL2 has been regarded as a potential target for abnormal proliferation in colorectal cancer." (PMID 34193109, 2021). "Moreover, one study has also indicated that FMNL2 could activate the Wnt/β-catenin to drive the progression of colorectal cancer." (PMID 34257650, 2021). "Some researchers provide evidences that circ_001569 acts mechanically as a miRNA sponge to inhibit miR-145 activity, and subsequently up-regulates miR-145 targets E2F5, BAG4 and FMNL2 to promote cell proliferation and invasion in CRC (colorectal cancer)." (PMID 28279183, 2017).
colorectal cancer (continued). "MicroR-206 also acts as a tumor suppressor in bladder cancer and colorectal cancer via targeting YRDC and FMNL2, which are closely related to the tumor cell proliferation and EMT." (PMID 28615991, 2017). "Likewise, hsa-circ-001569 may promote the proliferation and invasion of colorectal cancer cells by sponging miR-145 and subsequently upregulating the expression of E2F5, BAG4, and FMNL2." (PMID 31821171, 2019).
melanoma (13 papers, 2010 to 2024). A malignant, usually aggressive tumor composed of atypical, neoplastic melanocytes. "FMNL2 upregulation is associated with poor outcome in term of RFS or disease-specific survival in melanoma." (PMID 35379791, 2022). "Loss of FMNL2/3 function in melanoma cells and fibroblasts reduces lamellipodial width, actin filament density and -bundling, without changing patterns of Arp2/3 complex incorporation." (PMID 28327544, 2017). "We tested FMNL2-birA* expression in A375 human melanoma cells to determine if the presence of the birA* tag interfered with FMNL2 activity." (PMID 38891874, 2024). "We show directly, for the first time, that FMNL2 is present in the extracellular vesicles secreted by human melanoma cells." (PMID 38891874, 2024). "Our results show for the first time that FMNL2 is enriched in exosomes released by melanoma cells and highlight the potential for FMNL2 as a regulator of extracellular vesicle release." (PMID 38891874, 2024). "Our results confirm these reports and show, for the first time, that FMNL2 is enriched in melanoma cell exosomes." (PMID 38891874, 2024). "FMNL2 activity has recently been associated with exosome release downstream of an EGFL6 signaling pathway, and previous proteomic screens found FMNL2 in exosomes released by melanoma cells." (PMID 38891874, 2024). "We then sought to determine if the endogenous FMNL2 protein is present in ECVs released by melanoma cells." (PMID 38891874, 2024). "FMNL2 is required for melanoma cell migration, where it generates protrusive force to push forward the lamellipodia." (PMID 36259517, 2022). "The distinct phenotypes induced by IRTKS alone versus IRTKS coexpressed with FMNL2 are reminiscent of previous scanning electron microscopy studies of melanoma cell morphology." (PMID 36259517, 2022). "We noted that when transiently expressed in A2058 melanoma cells, FMNL2-mCherry displays a distinct subcellular localization along the length of the filopodia without an obvious concentration at the filopodia tip." (PMID 36259517, 2022). "We coexpressed FMNL2-mCherry with either FLAG-tagged IRTKS or IRSp53 in A2058 melanoma cells and assessed their effects on filopodia formation by immunofluorescence." (PMID 36259517, 2022). "Formin 1 (FMN1) is involved in the formation of adherens junctions and actin organization, and other formin family genes (FMNL2/FMNL3) have been shown to play a role in melanoma biology." (PMID 34281234, 2021). "Previous studies have suggested that especially FMNL2 participates in melanoma cell invasion by driving elongation of actin filaments that constitute the lamellipodia." (PMID 31039200, 2019). "In stage I-II melanoma patients, FMNL2 expression was an independent predictor of survival together with melanoma thickness." (PMID 31039200, 2019). "Other studies provided evidence for an interaction between FMNL2 and active Cdc42 and link FMNL2 functions to lamellipodial protrusions during migration of B16-F1 melanoma cells." (PMID 29579104, 2018). "FMNL2 has previously been shown to accumulate at the edge of lamellipodia and at the tips of filopodia in migrating B16-melanoma cells, where in conjunction with FMNL3, it regulates actin filament formation throughout the protruding lamellipodia." (PMID 29930204, 2018). "Strikingly, in melanoma cells, FMNL2/3 gene inactivation almost completely abolishes protrusion forces exerted by lamellipodia and modifies their ultrastructural organization." (PMID 28327544, 2017). "A key difference between the primary melanocytes and melanoma cells, however, is the variety of FMNL2 isoforms expressed." (PMID 27578625, 2016). "Surprisingly, the total level of FMNL2 expression in primary melanocytes was similar to that in the melanoma cell-lines." (PMID 27578625, 2016). "We find that a previously uncharacterized FMNL2 isoform is predominantly expressed in a variety of melanoma and CRC cell lines; this isoform is also more effective in driving 3D motility." (PMID 27578625, 2016).
melanoma (continued). "Increased FMNL2 expression correlates with increased invasiveness in CRC cell-lines and FMNL2 is consistently highly expressed across the NCI60 panel of melanoma cell-lines." (PMID 27578625, 2016). "In cultured melanoma cells, FMNL2 co-localizes with F-actin dots at the tips of cellular protrusions." (PMID 20633255, 2010). "In our study, confocal microscopy of WM164 melanoma cells revealed a co-localization of F-actin and FMNL2 at the tips of cell protrusions." (PMID 20633255, 2010). "In the same study, RhoC and FMNL2 were, by using RNA interference, found to be essential for the invasive motility of rounded human melanoma cells." (PMID 20633255, 2010). "FMNL2 is also part of the melanoma cell adhesome and promotes β1-integrin trafficking." (PMID 38891874, 2024). "Given the concordance of our results in both A375 and A2058 cell lines, we feel that our model for FMNL2–IRTKS cooperation may be generally applicable in human melanoma cells." (PMID 36259517, 2022). "We conclude that further studies are needed to confirm the role of FMNL2 in melanoma biology." (PMID 31039200, 2019). "Our results indicate that functions of FMNL2 in the establishment and maintenance of cell-cell contacts cannot be attributed to defects in the formation of actin-based membrane protrusions, which were recently described for FMNL2 in migrating B16-F1 melanoma cells." (PMID 29579104, 2018). "Here, we explored this hypothesis by combining comparative analyses of the biochemical activities of FMNL2 and FMNL3 with examination of the consequences of FMNL2/3 loss of function in migrating melanoma and fibroblast cells." (PMID 28327544, 2017). "Indeed, the level of total FMNL2 expression in SW620 cells is similar to that observed in the melanoma cell-lines." (PMID 27578625, 2016). "We also show that invasion by A375 and WM266.4 melanoma cells is FMNL2-dependent suggesting that FMNL2 might be generally required for 3D invasion in this cell-type." (PMID 27578625, 2016). "In melanoma cells, FMNL2 shows a distinct co-localization with actin dots in cellular protrusions." (PMID 20633255, 2010). "Furthermore, FMNL2 co-localized with F-actin to the tips of cellular protrusions in WM164 human melanoma cells." (PMID 20633255, 2010). "We show here that both IRTKS and IRSp53 cooperate with FMNL2 in filopodia assembly in human melanoma cells and that IRTKS and FMNL2 are mutually dependent cofactors in this process." (PMID 36259517, 2022). "Similar results were obtained with FMNL2 overexpression with IRTKS and IRSp53 in A375 human melanoma cells." (PMID 36259517, 2022). "In contrast, the TQS isoform predominates in invasive melanoma and CRC cell-lines and we find that knockdown of FMNL2 expression in A375 and WM266.4 melanoma cells is sufficient to inhibit invasion in an in vitro assay." (PMID 27578625, 2016). "FMNL2 is required in both MDA-MB-435 for amoeboid cell invasion in vitro and B16-F1 melanoma cells where it cooperates with the Arp2/3 complex for lamellipodial extension." (PMID 27578625, 2016). "Of the four isoforms, FMNL2.TQS is preferentially up-regulated in invasive CRC and melanoma cell-lines and is the most efficient in supporting cellular invasion." (PMID 27578625, 2016). "We show here that there are at least four of the predicted FMNL2 isoforms expressed in CRC and melanoma cells and that a novel isoform is preferentially up-regulated in invasive cells." (PMID 27578625, 2016). "Building on previous reports, we also show that FMNL2 is required for invasion in A375 and WM266.4 melanoma cells." (PMID 27578625, 2016). "In our study FMNL2-expression was not an independent prognosticator of sentinel node involvement or melanoma outcome in contrast to previous results." (PMID 31039200, 2019). "Using RT-PCR we identified four FMNL2 isoforms expressed in CRC and melanoma cell-lines." (PMID 27578625, 2016).
melanoma (continued). "This suggests an intriguing model where it is not the total level of FMNL2 expression that determines invasiveness in melanoma, but the specific isoform that is expressed." (PMID 27578625, 2016). "We show here that FMNL2 expression is required for invasion in A375 and WM266.4 melanoma cells and, taken with previous results, this suggests that FMNL2 is likely to be generally required by melanoma cells for invasion." (PMID 27578625, 2016). "Taken together, these results suggest that FMNL2 is likely to be generally required in melanoma cells for invasion, that a specific isoform of FMNL2 is up-regulated in invasive CRC and melanoma cells and this isoform is the most effective at facilitating invasion." (PMID 27578625, 2016). "Taken with previous reports that FMNL2 is required for migration in mouse B16 melanoma cells and for invasion in MDA-MB-435, our results suggest that FMNL2 is likely to be generally required for invasion in melanoma cells." (PMID 27578625, 2016).
breast carcinoma (9 papers, 2010 to 2024). "TIMER analysis indicated that FMNL2 expression was negatively associated with ER-related molecular subtyping in breast cancer; FMNL2 was low-expressed in luminal subtyping, but highly expressed in basal subtyping of breast cancer tissues." (PMID 35379791, 2022). "In this study, we mainly investigated the effects of FMNL2 on breast cancer cell migration and invasion, and the underlying mechanisms involved." (PMID 35379791, 2022). "We found that FMNL2 expression was positively associated with Ki67 among collected breast cancer tissues and in TCGA database." (PMID 34193109, 2021). "Our results also suggest that more attention should be paid to the pivotal role of FMNL2 in breast cancer progression, and especially the thorough underlying mechanisms." (PMID 34193109, 2021). "Thus, in this study we mainly explored the role of FMNL2 in cell migration and invasion of breast cancer, and the possible underlying mechanisms involved." (PMID 35379791, 2022). "We may infer that the cytoplasm/nucleus distribution of FMNL2 and p27 is associated with the cell proliferation of human breast cancer." (PMID 34193109, 2021). "Therefore, it was next investigated whether LIMK/Cofilin pathway and Rho-associated factors was involved in FMNL2-mediated breast cancer cell migration and invasion." (PMID 35379791, 2022). "In addition, the expression and prognosis of FMNL2 were associated with ER in breast cancer." (PMID 35379791, 2022). "However, the mechanisms underlying how FMNL2 regulates cell proliferation in breast cancer is currently unknown." (PMID 34193109, 2021). "We speculated that FMNL2 might be implicated in the malignant progression of human breast cancer." (PMID 34193109, 2021). "Further thorough and expanded research are needed to deeply explore the concrete molecular regulatory mechanisms concerning how ER affects FMNL2 expression in breast cancer." (PMID 35379791, 2022). "Our previous clinical data has revealed that FMNL2 expression is negatively correlated with ER in breast cancer." (PMID 35379791, 2022). "Overall, our results manifested that RhoA/LIMK/Cofilin pathway was involved in FMNL2 silencing-induced actin cytoskeleton rearrangement in breast cancer cells." (PMID 35379791, 2022). "We further demonstrated that FMNL2 silencing facilitated the actin cytoskeleton rearrangement in breast cancer cells that was necessary for cancer cell motility." (PMID 35379791, 2022). "Although the role of FMNL2 in various cancer metastasis and progression is still controversial, herein, our results demonstrated that FMNL2 was the potential of suppressing breast cancer metastasis, at least." (PMID 35379791, 2022). "In conclusion, FMNL2 suppressed cell migration and invasion of breast cancer by inhibiting RhoA/LIMK/Cofilin pathway through a reduction of cytoplasmic p27." (PMID 35379791, 2022). "In our previous work, FMNL2 promoted cell proliferation by reducing p27 nuclear localization and p27 protein stability in breast cancer cells." (PMID 35379791, 2022). "In the previous study, we confirmed that FMNL2 reduced the levels of cytoplasmic p27 in breast cancer cells." (PMID 35379791, 2022). "In this study, here we mainly focused on the effect of FMNL2 on cell proliferation and related mechanisms in human breast cancer cells." (PMID 34193109, 2021). "Firstly, we analyzed the clinical relevance between FMNL2 expression and clinicopathological variables in tumor specimens from breast cancer patients." (PMID 34193109, 2021). "In this work, we observed a significant positive correlation between FMNL2 and Ki67 in breast cancer samples." (PMID 34193109, 2021). "Taken together, these findings strongly reinforced that FMNL2 promoted cell proliferation partially by reducing p27 nuclear localization and p27 protein stability in human breast cancer cells." (PMID 34193109, 2021).